CRP (C-reactive protein)
Diseases named in the same sentence as CRP in open-access papers (continued):
Sharing a sentence is not in itself a finding about the gene and the disease.
Obesity (continued). "We did not include other biological (such as coronary calcium or C-reactive protein) or behavioral (such as obesity or exercise) risk factors because none are included in Framingham risk scoring currently used in cholesterol risk stratification and treatment guidelines." (PMID 21639906, 2011). "This study confirms that HS-CRP increases following smoking but there is a question whether smoking is the main cause of increase in CRP level in the patients or not and this study supports the role of obesity in increase of inflammation in COPD too." (PMID 22737409, 2011). "We then examined whether the possible protective effect of haplogroup H1 towards T2DM was related to age, gender, obesity, smoking, and/or to some clinical traits such as BMI, metabolic syndrome, insulin resistance, fibrinogen, C-reactive protein, HbA1c, HDL, triglycerides and hypertension." (PMID 21695278, 2011). "Additionally, recent evidence also suggests that obesity is characterized by a low-grade chronic inflammatory state, reflected by elevated levels in several serum inflammatory markers, such as interleukin-6 (IL-6) and C-reactive protein (CRP)." (PMID 20525285, 2010). "Fibrinogen levels are elevated in this high-risk urban Indigenous cohort, are associated with traditional and non-traditional cardiovascular risk factors and, although closely related to CRP, may not be influenced as much by obesity as is CRP (in men)." (PMID 21029470, 2010). "However, the relationships among obesity, CRP, and insulin resistance are complex." (PMID 21167068, 2010). "Obesity, particularly visceral adiposity, is accompanied by chronic low-grade inflammation, indicated by increased serum levels of inflammatory markers such as C-reactive protein (CRP), tumor necrosis factor-α (TNF-α), and interleukin-6 (IL-6) of obese patients." (PMID 22375203, 2010). "As a non-specific indicator of inflammation, CRP is also not a specific indicator of a single disease state such as cardiovascular disease but elevated concentrations can be seen in association with other comorbidities including obesity and pulmonary disease." (PMID 19690638, 2007). "Individuals with obesity consistently show elevated circulating IL-6, TNF-α, and C-reactive protein (CRP)." (PMID 41543809, 2026). "Interestingly, a meta-analysis of 50 lifestyle programs found that combining physical activity/exercise with dietary/nutritional changes is likely to lower CRP, IL-6, and IL-1β concentrations, and may also reduce IL-8 in healthy children and adolescents who have overweight or obesity." (PMID 41515266, 2026). "Obesity's chronic inflammatory milieu, with elevated IL-6, TNF-α, and CRP, compromises BBB integrity, facilitating immune cell infiltration and neuroinflammation." (PMID 41543809, 2026). "Elevated levels of inflammatory mediators, such as tumor necrosis factor alpha (TNF-alpha), interleukin-6 (IL-6), and C-reactive protein (CRP), are observed in obesity." (PMID 40218888, 2025). "Among the proinflammatory cytokines discussed, IL-6, CRP, and TNF-α appear to be the most promising candidates as potential biomarkers for depression, particularly in the context of obesity, where their levels are also elevated." (PMID 40507778, 2025). "Dairy products and dairy proteins have demonstrated efficacy in reducing inflammatory markers, including CRP, IL-6, TNF-α, and MCP-1, in individuals with obesity and overweight conditions." (PMID 40216734, 2025). "Obesity-related adipose tissue secrets pro-inflammatory cytokines such as tumor necrosis factor-alpha (TNF-α), interleukin-6 (IL-6), and C-reactive protein (CRP)." (PMID 40981180, 2025). "YKL-40 and CRP had similar prognostic abilities for obesity-related and gastrointestinal cancers, but YKL-40 outperformed CRP for liver and bladder cancers." (PMID 40188292, 2025).
Obesity (continued). "However, as serum LPS concentrations were measured only at the end of the experiment, it can only be speculated whether elevated LPS concentrations also preceded the onset of obesity and thereby contributed to the early increase in serum CRP concentrations in the HFFC group." (PMID 40770069, 2025). "In participants with obesity and overweight, eGDR was negatively correlated with age, CAP, BMI, WC, CRP level, WBC count, and liver stiffness (all P < 0.05)." (PMID 40158190, 2025). "In particular, differences in CRP, insulin, and HOMA-IR levels were significantly elevated in the obesity group, indicating a potential increase in systemic inflammation and insulin resistance (p = 0.001)." (PMID 41374089, 2025). "In addition, systemic oxidative stress induced by IR and obesity may activate a downstream inflammatory cascade, and patients with MetS have elevated levels of various inflammatory markers, including C-reactive protein (CRP) and interleukin (IL)-6." (PMID 40095232, 2025). "Smokers showed lower rates of obesity, lower HDL-cholesterol, and higher levels of CRP, triglycerides and HbA1c." (PMID 40635900, 2025). "This study investigates the role of inflammatory markers, specifically C-reactive protein (CRP) and neutrophil-to-lymphocyte ratio (NLR), in mediating the relationship between obesity and depressive symptoms." (PMID 40926826, 2025). "Higher CRP, SAA, calprotectin, age, BMI, obesity, systolic BP, and the use of antihypertensive drugs at baseline were all associated with higher LV mass index at follow up in univariable analyses (all p < 0.05)." (PMID 41141372, 2025). "Supporting this, studies on normal-weight subjects with obesity (NOW) have reported higher ALT in men, but higher CRP in women, compared to lean controls." (PMID 41007852, 2025). "Levels of C-reactive protein (CRP), erythrocyte sedimentation rate (ESR), and prothrombin time (PT) varied significantly among patients with mild, moderate, and severe obesity." (PMID 40491428, 2025). "Results indicated a positive correlation between obesity, NLR, and CRP levels, and depressive symptoms." (PMID 40926826, 2025). "For participants with obesity and overweight, eGDR was negatively correlated with age, CAP, body mass index (BMI), waist circumference, C-reactive protein level, and white blood cell (WBC) count (all P < 0.05)." (PMID 40158190, 2025). "As compared with individuals with normal weight, people with obesity exhibit higher postprandial glucose, insulin, TG, and inflammatory markers such as IL-6, TNF-α, and CRP." (PMID 41301434, 2025). "Inflammatory markers are considered closely related to obesity, and in our meta-analysis, we found that PBM can significantly reduce CRP levels [MD = − 0.99, 95% CI (− 1.17 to − 0.82), p < 0.00001]." (PMID 40217252, 2025). "It appears that leptin binds to circulating C-reactive Protein (CRP), an inflammatory marker that is increased in obesity." (PMID 38778593, 2025). "Both CRP and NLR are key indicators of systemicinflammation, which plays a crucial role in the pathway linking obesity anddepression." (PMID 40926826, 2025). "Using CCJ12, in vivo effects on bodyweight, cholesterol, HDL, LDL, and triglycerides, leptin, adiponectin, sE-selectin, CRP, MCP-1 and TNF-alpha factors were studied in a high fat diet-induced obesity rodent model." (PMID 40770283, 2025). "This pro-inflammatory state and cell imbalance observed in patients with obesity is the consequence of an increased production of adipokines, such as tumor necrosis factor alpha (TNF-a), interleukin-6 (IL-6), and C-reactive protein (CRP), by the adipocytes." (PMID 40435018, 2025). "Subject to data availability, only stratified meta-analysis on median C-reactive protein (CRP) levels and obesity [body mass index (BMI) ≥30 kg/m2] were performed." (PMID 40235956, 2025).
Obesity (continued). "A review of other studies has revealed that CRP may not be used as a good prognostic indicator due to its susceptibility to confounding from obesity and metabolic syndrome, both of which are prevalent in this patient population, as we discussed in the introduction section." (PMID 41458786, 2025). "Visceral adipose-derived IL-6 stimulates hepatic CRP production via STAT3 activation, creating a 2- to 3-fold increase in circulating CRP levels observed in obesity." (PMID 40699756, 2025). "Inflammatory factors within adipose tissue are linked to the mechanisms of obesity-related metabolic dysfunction, with elevated levels of C-reactive protein, TNF-α, and interleukin (IL)-6 accelerating the progression of chronic metabolic diseases in obesity." (PMID 40673005, 2025). "Obesity is characterised by a chronic low-grade inflammatory state and many biomarkers categorised as either metabolic (e.g., cholesterol, insulin resistance) or inflammatory (e.g., CRP, leptin, adiponectin) may reflect overlapping pathophysiological pathways linked to adiposity." (PMID 41050371, 2025). "The main inflammatory players in obesity are pro-inflammatory cytokines such as TNF-α, IL-6, and C-Reactive Protein (CRP), as well as adipokines such as leptin, adiponectin, resistin, among others secreted by adipose tissue." (PMID 41373779, 2025). "Individuals exhibiting frailty often display elevated levels of Interleukin-6 (IL-6), C-reactive protein (CRP), and Tumor Necrosis Factor-alpha (TNF-α), partially attributed to the prevalence of overweight/obesity in the elderly population." (PMID 40413725, 2025). "In obesity, pro-inflammatory adipocytes-derived cytokines (IL-6, TNF-α, and IL-1β) and C-reactive protein (CRP) are often elevated." (PMID 41375608, 2025). "Our previous clinical trial on individuals with obesity demonstrated that NAC supplementation significantly reduced serum IL-6 and CRP levels while downregulating p16 and IL6 gene expression in adipose tissue." (PMID 40421021, 2025). "Pregnant women with obesity and PE exhibit higher leptin levels, correlating with increased Tumor Necrosis Factor-Alfa (TNF-α), Interleukin 6 (IL-6), and C-reactive protein concentrations." (PMID 38750456, 2024). "Therefore, CRP could serve as a predictive indicator for both obesity and asthma." (PMID 39201554, 2024). "This panel of parameters encompasses the granulocyte-to-lymphocyte ratio (G/L ratio), C-reactive protein (CRP), ferritin, procalcitonin, age, and obesity status." (PMID 38793085, 2024). "We conducted a single SNP-GWAS to detect the association between each individual SNP and six phenotypic traits: obesity, HTN, T2D, DLP, CRP levels, and HDLc." (PMID 39717478, 2024). "Thus, high CRP levels were not necessarily associated with obesity." (PMID 38546019, 2024). "The current study evaluated the association between IH, low ferritin and inflammation parameters (interleukin 6 (IL-6), C-reactive protein (CRP), human chorionic gonadotrophin (hCG) and obesity." (PMID 38330593, 2024). "Thus, future studies investigating more closely the associations between vitamin C, CRP and weight/BMI appear warranted as changes in CRP may simply be reflecting changes in body weight/obesity, rather than a direct effect of vitamin C on CRP status per se." (PMID 38671852, 2024). "Obesity leads to the release of pro-inflammatory substances like tumor necrosis factor alpha (TNF-α), interleukin-6 (IL-6), and C-reactive protein (CRP), which induce the generation of ROS, resulting in elevated oxidative stress." (PMID 39194738, 2024). "IHCA is linked to conditions such as excessive alcohol consumption, metabolic syndrome, and obesity, along with heightened levels of inflammation-related proteins like serum amyloid A (SAA) and CRP." (PMID 38989373, 2024).
Obesity (continued). "The association between CRP and insulin resistance may be an epiphenomenon of obesity or adiposity, rather than an independent factor, and, in fact, a study of Korean subjects showed that slight weight gain (BMI ≥23 kg/m2) was a greater risk for insulin resistance than high CRP levels." (PMID 38188453, 2024). "However, variants in genes such as those encoding for cholesteryl transfer protein (CETP), CRP, and G protein-coupled inward rectifier K(+) channel 4 (GIRK4) have been shown to play crucial roles in influencing susceptibility to AF, particularly in the context of obesity." (PMID 38247541, 2024). "Both psoriasis and obesity induce the production of inflammatory markers and mediators, such as TNF-α, and produce pro-inflammatory cytokines, including C-reactive protein and IL-6." (PMID 39200092, 2024). "A meta-analysis encompassing 51 cross-sectional studies supports a positive correlation between C-reactive protein (CRP) and various obesity indicators, including BMI, waist circumference (WC), and waist-to-hip ratio." (PMID 39967714, 2024). "Tirzepatide and liraglutide lowered body weight, OSA severity, and serum C-reactive protein levels in adults with OSA and obesity." (PMID 41424495, 2024). "The main findings of the present study highlight the well-known proinflammatory status related to obesity and validated in our studied group through high levels of IL-18, MCP-1, CRP, monocytes, lymphocytes, and neutrophils compared with the control group." (PMID 40729297, 2024). "As a pro-inflammatory state, Obesity is characterized by elevated levels of inflammatory cytokines such as TNF-alpha, IL-6, and CRP." (PMID 39829729, 2024). "White fat inflammation was a major contributor to increased CRP in obesity, and OSA should be taken into consideration to explain the high CRP levels in obese patients." (PMID 36923793, 2023). "In conclusion, our meta-analysis demonstrated the beneficial effect of ALA supplementation on reducing CRP, TNF-α, SBP, and TG in individuals with obesity or overweight." (PMID 37778442, 2023). "This discrepant association between hypertension and CRP was strongly confounded by obesity, as the difference in effect size between EIS and CRP mostly disappeared after adjusting for participant BMI (CRP: 1.16 [1.02, 1.31]; EIS: 1.12 [0.99, 1.27])." (PMID 37139638, 2023). "In the study of obesity and chronic inflammation, some scholars used TNF-α, CRP, and hs-CRP to evaluate chronic inflammation." (PMID 37582770, 2023). "The strength of our study is expressed when examining the relationship between selected measures of obesity (BMI, WC, RFM, VAI, WHtR) and parameters of chronic inflammation (CRP, TNF-α, IL-6) in perimenopausal healthy women." (PMID 37375693, 2023). "Obesity unfavorably influences the relationship between blood and GCF CRP levels and promotes increased CRP levels in GCF." (PMID 38138192, 2023). "The reported connection of inflammation with depression, obesity, and HTG is corroborated in our analysis where CRP levels were found to be higher in these conditions compared with the control populations." (PMID 38455932, 2023). "Obesity in SLE increases the expression of interleukin 23 (IL-23), tumor necrosis factor alpha (TNF-α), IL-6, and C-reactive protein (CRP)." (PMID 36839394, 2023). "People with class 4 obesity presented higher mean weight, BMI, WC, VF, glucose, LDL-c (only a significant difference by sex) TG, CRP, and systolic blood pressure (SBP)." (PMID 37334132, 2023). "The reported association of chronic low-grade inflammation with depression, obesity, and HTG also motivated us to explore any connection of CRP with PHQ-9 score, BMI, and triglyceride level." (PMID 38455932, 2023). "Among these risk factors, 10 have been the subject of repeated studies: Type 2 diabetes, thyroid function, BMI, obesity, smoking, SUA, O6FA, CRP, LDL‐C, and telomere length." (PMID 37724687, 2023).
Obesity (continued). "C-reactive protein (CPR) is a pentraxin protein primarily synthesized and secreted by the liver and released into the bloodstream in response to inflammation in obesity." (PMID 37608837, 2023). "Obesity-related parameters, such as BMI, waist circumference, body fat, visceral fat, triglyceride levels, HOMA-IR index, and C-reactive protein were studied." (PMID 37522130, 2023). "Patients with obesity and type 2 diabetes showed significant reductions in TNF-α, IL-6, CRP, conjugated dienes, and MDA in addition to significant rises in GPx, SOD, and GSH after three months of a lifestyle intervention (diet and physical activity)." (PMID 37109709, 2023). "Accordingly, the goal of this narrative review is to summarize the effects of TRE and ADF on body weight and key circulating inflammatory markers, i.e., CRP, TNF-alpha, and IL-6, in adults with overweight and obesity." (PMID 37139450, 2023). "During obesity, the inflamed VAT is a source of pro-inflammatory adipokines including tumour necrosis factor (TNF)-α, IL-6, IL-8, CRP, or leptin, among others, that are released into the circulation promoting systemic inflammation." (PMID 36831381, 2023). "In this RCT among participants with T2D and overweight/obesity, GCE supplementation with doses of 800 mg/d for 10 weeks led to a significant decrease in weight, BMI, SBP, HOMA-IR, serum TG, and CRP levels, and a significant increase in serum HDL levels." (PMID 38035358, 2023). "Since the subjects with depression, obesity, and HTG showed higher CRP values in cumulative distribution plots, we first studied their prevalence across the CRP groups." (PMID 38455932, 2023). "Cumulative distribution plots of CRP revealed higher values in populations with depression, obesity, and HTG with the difference being most prominent for obesity." (PMID 38455932, 2023). "Individuals with obesity displayed increased adipose TNF-α gene/protein expression as well as elevated plasma levels of TNF-α, CRP, MDA, and OX-LDL (p ≤ 0.05)." (PMID 37894865, 2023). "These factors include Type 2 diabetes, thyroid function, BMI, obesity, smoking, serum uric acid (SUA), omega‐6 fatty acids (O6FA), C‐reactive protein (CRP), LDL‐C, and telomere length." (PMID 37724687, 2023). "Serum CRP levels in children with normal body weight (0.10; IQR 0.10–0.38 mg/L) were significantly lower than in those with obesity and MetS (1.10; IQR 0.33–3.50 mg/L, p<0.0001)." (PMID 36920931, 2023). "In a two-decade prospective follow-up study, the cardiometabolic profile (HOMA-IR, hs-CRP, and serum HDL) was more adverse in recent-onset obesity and persistent obesity youths (23 years old) compared to never obese participants." (PMID 35563955, 2022). "Elevated plasma levels of C-reactive protein (CRP) and pro-inflammatory cytokines such as IL-6, TNF-α, MCP-1, IL-8, and IL-7 confirmed the existence of an inflammatory state in individuals with obesity." (PMID 35896710, 2022). "Several studies have observed increased inflammatory proteins, such as C-reactive protein, which declined after bariatric surgery in T2DM patients with obesity." (PMID 36619535, 2022). "With the increase of various inflammatory factors in serum, such as C-reactive protein (CRP), IL-6, and tumor necrosis factor-α (TNF-α), obesity is essentially a chronic low-grade inflammatory state that is difficult to eliminate." (PMID 36105933, 2022). "Researchers indicated that obesity should play a vital role in the increased secretion of cytokines such as IL-1, IL-6, IL-8, TNF-α, and CRP, and further lead to chronic low-grade inflammation." (PMID 36613000, 2022). "The presence of elevated concentrations of serum C-reactive protein (CRP), IL-6, TNF-α, leukocyte and higher neutrophil count in obesity-induced chronic inflammation results in the accumulation of macrophages in the adipose tissue of obese individuals." (PMID 35328822, 2022).